NFATC1 (nuclear factor of activated T cells 1)
Diseases named in the same sentence as NFATC1 in open-access papers (continued):
Sharing a sentence is not in itself a finding about the gene and the disease.
bladder cancer (6 papers, 2015 to 2023). "In this study, we built a machine learning-based model to directly predict PD-L1-high bladder cancers based on the methylation level of NFATc1 and achieved an AUC score of 0.884." (PMID 37138354, 2023). "We also observed a series of 5mC hypo differentially methylated regions (DMRs) in the gene body of NFATC1, which is highly involved in T-cell immune responses in bladder cancer samples with high expression of PD-L1." (PMID 37138354, 2023). "To investigate the effects of AHNAK and NFATC1 on the biological functions of bladder cancer cells, we performed transwell and MTT assays." (PMID 35958586, 2022). "We therefore performed a scratch wound healing assay and a transwell invasion assay to assess the effects of NFATc1 inhibition on cell migration and invasion, respectively, in bladder cancer lines." (PMID 25638160, 2015). "We determined the effects of CsA and FK506, which were known to inhibit NFAT signals in immune cells, on NFATc1 expression by western blotting, RT-PCR, and immunofluorescence in bladder cancer cells." (PMID 25638160, 2015). "Our staining results thus support other data suggesting that NFATc1 promotes bladder cancer progression." (PMID 25638160, 2015). "Further assessment of the functions of NFATc1 as well as other isoforms is required to determine biological significance of NFAT signaling in bladder cancer." (PMID 25638160, 2015). "All four bladder cancer lines were found to express NFATc1 at both protein and mRNA levels, and its expression in the benign urothelial line was weaker." (PMID 25638160, 2015). "Using bladder cancer lines, we here demonstrated that they overexpressed NFATc1 and that silencing of NFATc1 resulted in significant decreases, similar to those by CsA or FK506 treatment, in cell viability and invasion." (PMID 25638160, 2015). "The correlation between NFATc1 and PD-L1 expression is similar in bladder cancer." (PMID 37138354, 2023). "According to our results, hypomethylation of the NFATc1 gene body was observed in bladder cancer cells, indicating an activating state of NFATc1 transcription, and this state could be used to predict PD-L1 expression." (PMID 37138354, 2023). "Therefore, we experimentally validated the functions related to EMT, glycolysis, glutamine metabolism and immune checkpoint regulation of AHNAK and NFATC1 in bladder cancer." (PMID 35958586, 2022). "In the current study, we investigated whether NFATc1 inactivation inhibited the growth of bladder cancer cells." (PMID 25638160, 2015). "In conclusion, NFATc1 likely plays an important role in bladder cancer progression." (PMID 25638160, 2015). "Similarly, CsA and FK506 both at 1 μM reduced NFATc1 gene expression in all bladder cancer cell lines tested." (PMID 25638160, 2015). "We confirmed this in bladder cancer cells by demonstrating that CsA and FK506 reduced the overall and nuclear levels of NFATc1 expression, suppressed the transcriptional activity of NFAT, and down-regulated the expression of COX-2 and c-myc." (PMID 25638160, 2015). "To further verify our hypothesis, we transfected bladder cancer T24 cell with designed si HDAC4, si NFATC1 and si CBX7." (PMID 34405021, 2021). "Our findings may also offer a potential therapeutic strategy for bladder cancer via targeting the calcineurin-NFAT pathways, especially NFATc1 signals." (PMID 25638160, 2015). "Thus, NFATc1 inactivation, especially using CsA and FK506, has the potential of being a therapeutic approach for bladder cancer." (PMID 25638160, 2015). "Interestingly, these effects of CsA and FK506 were not seen in NFATc1 knock-down cell lines, suggesting that these non-selective NFAT inhibitors suppress bladder cancer growth predominantly through the NFATc1 pathway." (PMID 25638160, 2015).
bladder cancer (continued). "To determine whether NFATc1 down-regulation exerts an influence on the proliferation of bladder cancer cells, we assessed cell viability [by methylthiazolyldiphenyl-tetrazolium (MTT) assay] and colony formation (by clonogenic assay) in bladder cancer lines treated with CsA or FK506." (PMID 25638160, 2015). "In bladder cancer cell lines, cyclosporine A (CsA) and tacrolimus (FK506), immunosuppressant drugs/non-selective NFAT inhibitors, attenuated NFATc1 expression and its nuclear translocation, NFAT transcriptional activity, and the expression of cyclooxygenase-2 and c-myc, downstream targets of NFATc1." (PMID 25638160, 2015).
glomerulosclerosis (6 papers, 2011 to 2023). A hardening of the kidney glomerulus caused by scarring of the blood vessels. "Meanwhile, a steady-state expression of TRPC6, a known pathogenic factor of glomerulosclerosis, is increased through a pathway dependent on NFATc1." (PMID 29038896, 2018). "It has also been recently shown that NFATc1 may play roles in UB branching and glomerular development, and that conditional activation of NFATc1 in developing podocytes causes glomerulosclerosis." (PMID 21295565, 2011). "In addition, genetic overexpression of ABCA1 or cholesterol depletion was sufficient to attenuate TNF-induced albuminuria and prevent DKD progression in mice with podocyte-specific nuclear factor of activated T cells 1 (NFATc1) activation, a new model of glomerulosclerosis resembling DKD." (PMID 37242602, 2023). "Similarly, we found that podocyte-specific constitutively active NFATc1 increased uPAR expression and identified podocyte uPAR as a downstream target of NFAT in the pathogenesis of glomerulosclerosis." (PMID 29038896, 2018). "Because NFAT signaling mediates regulation of factors important for podocyte function and glomerulosclerosis, we explored whether ATF3 has a direct role in regulating NFATc1 gene promoter activity." (PMID 29038896, 2018).
Hodgkins lymphoma (6 papers, 2012 to 2025). A heterogeneous group of malignant lymphoid neoplasms of B-cell origin characterized histologically by the presence of Hodgkin and Reed-Sternberg (HRS) cells in the vast majority of cases. "The aims of this research are to evaluate the expression and distribution of NFATc1 in tumor microenvironment of Hodgkin lymphoma." (PMID 34181355, 2021). "In human Hodgkin ́s lymphoma cell lines in which the NFATC1 gene is suppressed all CpG residues of P1 were found to be fully methylated, whereas in Jurkat T cells they are de-methylated." (PMID 22764736, 2012). "Together our results may identify NFATc1 as promising target for alternative novel marker of prognostic and or predictive factors of Hodgkin lymphoma." (PMID 34181355, 2021). "However, this does not exclude that the expression of human NFATC1 gene is switched off in classical Hodgkin ́s lymphoma cells in which BCR signalling is suppressed, and NFATc3 can function as a tumor-suppressor for retrovirus-induced T cell lymphomas." (PMID 22764736, 2012).
melanoma (6 papers, 2009 to 2025). A malignant, usually aggressive tumor composed of atypical, neoplastic melanocytes. "Specifically, increased calcium influx triggered the nuclear translocation of NFATc1, which subsequently downregulated the transcription factor ATF3, leading to melanoma apoptosis." (PMID 37198657, 2023). "Increased calcium influx triggered the nuclear translocation of NFATc1, subsequently downregulated the transcription factor ATF3, and consequently led to melanoma apoptosis." (PMID 37198657, 2023). "In melanoma, CXCL8 expression can be regulated by nuclear factor of activated T-cells 1 (NFAT1), signal transducer and activator of transcription 3 (STAT3) and WNT signaling pathway." (PMID 32466509, 2020).
osteoarthritis (6 papers, 2014 to 2023). A noninflammatory degenerative joint disease occurring chiefly in older persons, characterized by degeneration of the articular cartilage, hypertrophy of bone at the margins and changes in the synovial membrane. "The expressions of RANKL and NFATC1 increased in synovial tissues of RA compared to osteoarthritis (OA) synovial tissues." (PMID 33952303, 2021).
viral infection (6 papers, 2015 to 2025). "These early alterations in the transcriptional landscape exclusively in NFATc1 knockout cells may explain the subsequent NFATc1-dependent loss of memory inflation during the later stages of virus infection." (PMID 38346075, 2024). "NFATC1 is a central TCR-induced TF that is particularly essential for Tfh differentiation during acute viral infection and maintenance of Tfh function during chronic GC responses in mice." (PMID 41427421, 2025). "We found that NFATc1 is crucial for maintaining persistent CD8+ T cell responses during chronic virus infection." (PMID 38346075, 2024). "Interestingly, NFATc1 and NFATc2 deficient OTI cells were able to control the virus infection as efficiently as WT OTI cells." (PMID 38346075, 2024). "Our data suggested that NFATc1 signaling promotes KLRG1+CD27- T cell differentiation and memory inflation during chronic virus infection." (PMID 38346075, 2024). "Collectively, our data highlight the overlap of key significant genes such as DGKA (NK and T-cell viral infection), EGR2 (T-cell viral infection and CD8 T-cell exhaustion), and the potential role of key TFs including EGR2, NFAT2 (NFATc1), and TOX2 in driving NK cell anergy." (PMID 38637625, 2024). "Following acute virus infection, the total CD8+ and CD4+ T cell response remained unaffected by the absence of NFATc1 or NFATc2 in the spleen or lymph nodes at 7 dpi." (PMID 38346075, 2024).
colitis (5 papers, 2012 to 2024). Inflammation of the colon. "In fact, NFATc1 and c2 deficient mice display impaired Th1 and Th2 response, and NFATc2 deficiency has been reported to suppress colitis induced by oxazolone administration." (PMID 22479554, 2012). "In harmony with previous studies, our results showed significant up-regulation of NFATC1 expression with higher histopathological scores in mice with oxazolone-induced colitis, in addition to the induced extensive inflammatory response evidenced by enhanced IL-13 production." (PMID 37902927, 2024). "Our results revealed that DCA significantly reduced the level of NFATC1 by 50% and NLRP3 by 40% in oxazolone-induced colitis." (PMID 37902927, 2024). "Non-canonical WNT pathway elements represented by FZD5, WNT5A and NFATc1 were remarkably elevated in colitis IELs." (PMID 26652024, 2015).
diffuse large B-cell lymphoma (5 papers, 2012 to 2024). "For diffuse large B-cell lymphomas (DLBCL) and pancreatic cancer cells an NFATc1-directed up-regulation of the MYC gene has been described which appears to be due to the recruitment of histone acetylases to the MYC promoter." (PMID 22764736, 2012).
heart failure (5 papers, 2015 to 2024). Inability of the heart to pump blood at an adequate rate to meet tissue metabolic requirements. "Consistent with this, Nfatc1 knockout mice die mid-gestation due to endocardial valve malformation-induced heart failure." (PMID 26153229, 2015). "In a mouse model of heart failure, blocking VEGF-C/VEGFR-3-mediated signals (AKT/ERK1/2, calcineurin A/NFATc1/FOXc2 and CX43) resulted in decreased cardiac lymphangiogenesis and increased cardiac dysfunction." (PMID 36064450, 2022).
osteosarcoma (5 papers, 2014 to 2025). A usually aggressive malignant bone-forming mesenchymal neoplasm, predominantly affecting adolescents and young adults. "PHOSPHO1 is specifically expressed in bone lesions, and NFATC1 is associated with normal osteocyte function and osteosarcoma pathogenesis." (PMID 36619306, 2022). "In addition, protein c-Fos is intimately related to the occurrence and growth of osteosarcoma, and in the process of osteoclast division, c-Fos is an important adjusting factor of RANKL downstream, which promotes osteoclast shaping mainly by activating the downstream factor NFATc1." (PMID 35267996, 2022).
acute myeloid leukemia (4 papers, 2018 to 2025). Acute myeloid leukemia (AML) is a group of neoplasms arising from precursor cells committed to the myeloid cell-line differentiation. "In human acute myelogenous leukemia, high NFATc1 expression is associated with poor prognosis." (PMID 37248542, 2023).
allergies (4 papers, 2018 to 2025). "NIP45, a transcription factor regulating NFATc1 activity, mRNA was found to be induced in the Peripheral Blood mononuclear cells (PMBCs) of asthmatic pre-school children with allergies and in the peripheral blood CD4+ T cells from adult asthmatic patients." (PMID 31666531, 2019). "Our data support the notion that targeting NFATc1 during allergic reactions may be explored for future therapeutic strategies in allergic diseases." (PMID 40943049, 2025). "However, our findings that NK-4 inhibited IL-4 and IL-5 secretion by Th2 cells through down-regulating GATA-3 and NFATc1 mRNA expression suggest that NK-4 could be an effective strategy for the treatment of Th2-mediated allergic disease." (PMID 29933387, 2018). "We recently described increased NFATc1, IRF4, and NIP45 messenger RNA (mRNA) expression in peripheral blood mononuclear cells (PBMCs) of asthmatic children and adults with multiple allergies." (PMID 33079489, 2020).
congenital heart disease (4 papers, 2012 to 2024). "The region related to congenital heart disease is 18q22.3q23, and the possible main pathogenic gene is NFATC1." (PMID 36123715, 2022). "Our results go along with what is published in that regard by adding the NFATC1 gene to the list of mutated genes linked to congenital heart disease in humans, particularly valve diseases." (PMID 23226213, 2012). "For instance, polymorphisms in NFATc1 associated with congenital heart disease may lead to impaired nuclear translocation and DNA binding affinity." (PMID 29499052, 2018).
hepatocellular carcinoma (4 papers, 2018 to 2022). A malignant tumor that arises from hepatocytes. "NFATc1 and FasL expression patterns and their prognostic value for patients with HCC were also evaluated in TCGA Liver Hepatocellular Carcinoma database." (PMID 30085405, 2018).
Hypertension (4 papers, 2013 to 2023). The presence of chronic increased pressure in the systemic arterial system. "Of those, 28 genes had more than 5 var-HpaII sites, and several of those have been reported the association with PE (PTPRN2, KCNMA1, and NFATC1), hypertension (SDK1), and placental development (SALL3)." (PMID 27293492, 2016).
pancreatic ductal adenocarcinoma (4 papers, 2017 to 2026). An infiltrating adenocarcinoma that arises from the epithelial cells of the pancreas. "Furthermore, Chen NM and colleagues found that KRAS signaling was required for EZH2-mediated transcriptional activation of the inflammatory transcription factor nuclear factor of activated T cells 1 (NFATC1) in pancreatic ductal adenocarcinoma cells." (PMID 29335012, 2018). "Using pancreatic ductal adenocarcinoma as a model system, we performed a SMAD4-focused oncogenic protein–protein interaction mapping and uncovered a novel interaction between SMAD4 and NFATc1." (PMID 40856537, 2026).
postmenopausal osteoporosis (4 papers, 2019 to 2025). Metabolic disorder associated with fractures of the femoral neck, vertebrae, and distal forearm. "This suppression reduces the expression of key osteoclast markers like NFATc1 and cathepsin K, leading to increased bone density in ovariectomized rats, a common model of postmenopausal osteoporosis." (PMID 40243497, 2025).
tricuspid atresia (4 papers, 2012 to 2025). Tricuspid atresia is (TA) a rare congenital heart malformation characterized by the congenital agenesis of tricuspid valve leading to severe hypoplasia of right ventricle (functionally univentricular). "Although the function of these genes on human heart development is still poorly studied, two heterozygous mutations in NFATC1 were recently reported in a patient with tricuspid atresia, and another recent study supported that NFATC1 plays an important role in cardiac development." (PMID 25516202, 2014). "Patients in Group 1, the tricuspid atresia group, carried variants in the BMP2, MYH6, NFATC1, NOTCH1, and ZFPM2 genes, which have been reported to be associated with tricuspid atresia." (PMID 41153298, 2025). "Moreover, genetic and structural genomic alterations in NFATC1 have already been identified in patients with CHD such as VSD or tricuspid atresia." (PMID 33276527, 2020).
ulcerative colitis (4 papers, 2011 to 2024). An inflammatory bowel disease involving the mucosal surface of the large intestine and rectum. "Nucleo-translocation/activation of NFATc1 in lamina propria mononuclear cells was found in ulcerative colitis." (PMID 26652024, 2015). "Recently, activation of NFATc1 was noted specifically in the mononuclear cells of the inflamed colonic mucosa from patients with ulcerative colitis." (PMID 21603612, 2011).
Chagas disease (3 papers, 2009 to 2024). A parasitic infection caused by Trypanosoma cruzi. "We identified Bcl2, Gsk3, Nfat5, and Nfatc1 as key players in Chagas disease pathogenesis, and our bioinformatics analysis identified 15 signaling pathways related to Chagas disease development." (PMID 39770386, 2024).
cherubism (3 papers, 2018 to 2020). Cherubism is a rare, self-limiting, fibro-osseous, genetic disease of childhood and adolescence characterized by varying degrees of progressive bilateral enlargement of the mandible and/or maxilla, with clinical repercussions in severe cases. "Mutations in NFATC1 are linked to Cherubism, a disorder characterized by abnormal bone tissue in the lower part of the face and a characteristic facial phenotype." (PMID 30631343, 2018). "TRAP activity, NFATc1 staining and the number of nuclei in CD68+ cells, strongly suggesting an osteoclastic phenotype, seem to be associated with the aggressiveness of cherubism." (PMID 30236129, 2018). "In human cherubism, three previous studies demonstrated the involvement of NFATc1, showing an increase in NFATc1 transcription in cherubism granuloma and nuclear expression of NFATc1 in MGC." (PMID 30236129, 2018). "As cherubism was recently described as being an auto-inflammatory bone disease, we focused on the expression of genes involved in osteoclastogenesis (RANK, RANKL, M-CSF, OPG, NFATc1), bone formation (ALP, Osteocalcin), and inflammation (IL6, IL6R, TNFα, TNFR1, TNFR2, IL17)." (PMID 30236129, 2018).
chronic lymphocytic leukemia (3 papers, 2017 to 2021). "Hypomethylation of the promoter region of NFATC1 was identified in chronic lymphocytic leukemia patients and found to correlate with disease stage." (PMID 30901947, 2019).